FH (fumarate hydratase)
Diseases named in the same sentence as FH in open-access papers (continued):
Sharing a sentence is not in itself a finding about the gene and the disease.
tumor (continued). "Energy metabolism favours oxidative phosphorylation and the tricarboxylic acid (TCA) cycle (OGDHL, PCK1, ACO1, FH) over glycolysis, limiting tumour growth." (PMID 41007296, 2025). "In the FH−/− tumor microenvironment, the accumulated fumarate can induce ZAP70 succination which decreases T cell activation." (PMID 41427347, 2025). "Utilising stochastic optical reconstruction microscopy (STORM), we pinpoint the sites of interaction to the mitochondria, thereby demonstrating a regulation of FH activity in tumour cells following HDAC6 inhibition." (PMID 40721560, 2025). "Mechanistically, RBM15 depletion increases the expression of fumarate hydratase (FH), which in turn decreases the level of fumarate, a known suppressor of anti-tumor immunity." (PMID 40370450, 2025). "Conversely, fumarate depletion by increasing the expression of fumarate hydratase (FH) in tumor cells dramatically enhances the anti-tumor cytotoxicity of chimeric antigen receptor (CAR) T cells." (PMID 40370450, 2025). "Our results indicated that FH is significantly downregulated in ccRCC compared to normal tissues, and its expression level inversely correlates with tumor stages I–IV." (PMID 40461489, 2025). "Together, these results identify HDAC6 inhibition as a regulator of endogenous FH activity in tumour cells, and highlight it as a promising candidate for indirectly targeting tumour metabolism." (PMID 40721560, 2025). "Fumarate hydratase (FH) is an enzyme involved in the tricarboxylic acid cycle and is a tumor suppressor gene." (PMID 40362376, 2025). "The in vivo tumor experiments in mice showed a two‐ to threefold reduction in the 13C‐malate/13C‐fumarate ratio following knockdown of FH expression using shRNA." (PMID 40331406, 2025). "In this study, we found that FH is markedly downregulated in ccRCC, with its expression level negatively correlating with tumor stages and positively correlating with patient prognosis." (PMID 40461489, 2025). "The smaller reduction in enzyme activity in vivo compared to in vitro following shRNA knockdown likely reflects the contributions from cells within the tumor microenvironment that have normal FH expression, such as the stroma, immune cells, or vascular tissue." (PMID 40331406, 2025). "There was also an association between survival and FH copy number amplification, with FH-amplified tumours showing a reduction in patient survival." (PMID 40721560, 2025). "In three patientswith aberrant tumor fumarate:malate, next-generation sequencing (NGS)revealed heterozygous likely pathogenic germline FH variants(0.8%)." (PMID 39705504, 2024). "Our tumor cells exhibited positive granular, cytoplasmic reactions for SDHB and loss of FH expression, with FH+ endothelial cells serving as a positive internal control." (PMID 38793008, 2024). "For example, genetic alterations in enzymes like succinate dehydrogenase (SDH), fumarate hydratase (FH), and isocitrate dehydrogenase (IDH) are linked to tumor development and progression." (PMID 39408832, 2024). "In most cancers, TOMM40 and FH were upregulated in the tumor group, suggesting that TOMM40 and FH play an important role in malignant proliferation and invasion." (PMID 38285218, 2024). "Mutations in FH, similar to SDH mutations, impede PHD activity, thereby stabilizing HIFα to facilitate the adaptation of tumor cells to hypoxic conditions." (PMID 39584783, 2024). "The mRNA expression levels of FH were significantly lower in tumor tissues than in adjacent normal tissues, according to TIMER 2.0." (PMID 38398104, 2024). "Strong positive staining for FH was observed in the studied tumor, indicating that the mutant protein was stable and detectable using the anti-FH antibody." (PMID 38721148, 2024). "Based on these results, a heterozygous germline variant, NM_000143: c.747T>A, p.S249R (chr1:241669460), was identified in the FH gene, with a variant allele frequency (VAF) of 0.57 in tumor and 0.45 in lymph node." (PMID 38721148, 2024).
tumor (continued). "Loss of FH expression indicates the presence of mutations in tumor cells, with SDHB applied as an additional marker to confirm the results of FH loss." (PMID 38793008, 2024). "FH loss also triggers oncogenic processes such as EMT and epigenetic reprogramming, underscoring its role as a tumor suppressor." (PMID 39494346, 2024). "Our further experimental results showed that protein and mRNA expression levels of FH in tumor tissues were significantly lower than in normal tissues." (PMID 38398104, 2024). "Our in vivo experiments showed that the knockdown of FH affected the volume and magnitude of tumor regression after PD-1 immunotherapy and PCSK9 inhibition reversed the effect of immunotherapy." (PMID 38398104, 2024). "Based on the multivariate analysis, advanced tumor invasiveness (hazard ratio = 4.22, p < 0.01) and low s-FH-Ab levels (hazard ratio = 3.02, p < 0.01) are independently associated with poor prognosis." (PMID 38791507, 2024). "In terms of treatment, FH-deficient RCC is highly invasive, and metastasis can occur when the tumor is less than 3 cm." (PMID 37076922, 2023). "Taking advantage of highly sensitive MS-based metabolic profiling, we identified 2 robust circulating biomarkers, succinic-cysteine (suc-cys) and succinyl-adenosine (suc-ado), which can sensitively and specifically reflect FH status and tumor burden in RCC." (PMID 37053010, 2023). "Research has revealed that the fumarate hydratase enzyme coded by the FH gene is not only vital to the Krebs cycle but also acts as a tumor suppressor." (PMID 37663422, 2023). "Their plasma concentrations reflected the biallelic inactivation of FH and correlated with tumor burden." (PMID 37053010, 2023). "Immunohistochemical analysis was performed to detect the expression levels of Ki-67, caspase-3, and fumarate hydratase in tumor tissues." (PMID 38139831, 2023). "For instance, mutations in the enzyme Fumarate hydratase (FH), Succinate dehydrogenase (SDH) and Isocitrate dehydrogenase (IDH), cause hereditary and sporadic tumours." (PMID 37689804, 2023). "Still, FH variants in HLRCC patients lead to loss of function, and the consequent LOH in the tumour tissue causes the complete loss of its enzymatic activity." (PMID 37689804, 2023). "Regarding the mechanism, FH depletion in tumor cells can accumulate fumarate in tumor interstitial fluid." (PMID 37675097, 2023). "FH is a tumor suppressor gene located at chromosome region 1q42.3-43 which encodes the enzyme fumarate hydratase, which plays a critical role in both the tricarboxylic acid (TCA) cycle in mitochondria and DNA double-strand breaks in the nucleus." (PMID 36981015, 2023). "In line with this, FH-deficient RCC, especially metastatic lesions, have been shown to be highly immunogenic, characterised by increased tumour T-cell infiltration but high expression of immune checkpoint cytokines." (PMID 37689804, 2023). "IHC performed on tumor biopsies with antibodies against S-(2-succino)-cysteine (2SC) in combination with anti-FH antibody is a sensitive assay, although its specificity still needs to be validated." (PMID 37053010, 2023). "One PDX originated from a left renal mass from a male patient with FH-MT, who was diagnosed with a germline alteration of FH c.823G>A (p.G275R), whereas the FH-WT control tumor was from a right kidney lesion from a patient with ccRCC." (PMID 37053010, 2023). "FH-deficient cells harbor lower fumarate and preserve Aconitase 2 (ACO2) function to promote tumor progression." (PMID 36778129, 2023). "Functional experiments revealed the role of FH in altering tumor glycolysis and in impacting PDAC tumor microenvironments." (PMID 36434634, 2022). "There was a higher M2:M1 ratio in cluster 1 (SDHx, VHL, FH, n = 27) tumours compared to cluster 2 (RET, n = 6) (P = 0.017) and a lower proportion of CD8 cytotoxic (Tc) lymphocytes in PPGLs with a known genetic diagnosis (P = 0.047)." (PMID 35975974, 2022).
tumor (continued). "Meanwhile, we found that the cell lines with FH knock down showed significantly higher tumor cell proliferation rates under high glucose condition, comparing to low glucose condition." (PMID 36434634, 2022). "This study is aimed at analyzing the prognostic value of FH and demonstrating the correlation between FH expression and tumor immunity." (PMID 34737838, 2021). "For instance, the glutaminase inhibitors were effective in reducing the growth of SDH and FH-deficient cancers by lowering the glutamine needed to replenish TCA intermediates including the R-2HG in IDH mutant tumours." (PMID 34070384, 2021). "Several studies reported germline mutations in other susceptibility genes for PPGLs, such as FH, SLC25A11, and MDH2, which were associated with aggressive tumor behavior." (PMID 34833055, 2021). "The promiscuous reactions of lactate dehydrogenase (LD), pyruvate dehydrogenase (PD) and fumarate hydratase (FH), produce (2S)-HG under acidic conditions, which is often observed in tumour and stem cells." (PMID 34854890, 2021). "There are also several mutations in TCA cycle enzymes associated with tumor proliferation, including mutations in aconitase (ACO2), citrate synthase (CS), succinate dehydrogenase (SDH), fumarate hydratase (FH), and isocitrate dehydrogenase (IDH)." (PMID 33946927, 2021). "In germline BRCA1/BRCA2/RAD51C/RAD51D/BRIP1 PVs, 44.4% (24/54) had a positive FH compared to 11.3% (28/249) of sporadic tumours (p < 0.001)." (PMID 34503154, 2021). "Next, the FH level between tumor tissues and normal tissues in 20 types of cancers was obtained from TCGA database." (PMID 34737838, 2021). "This implies that the FH protein expression level is high in our model, which is an important finding because FH is known to be a tumour suppressor, and fumarate has been reported as an oncometabolite." (PMID 32747645, 2020). "The required FH expression level for maintaining the oxidative TCA cycle is much lower than the actual expression level, which preserves the anti-tumour function of FH until complete loss of function." (PMID 32747645, 2020). "In particular, fumarate, that accumulates in FH-deficient tumors as type II CIMP-RCC and HLRCC, can directly succinate both KEAP1 and DJ-1 modulating NRF2, with a different impact on tumor growth and survival." (PMID 33233657, 2020). "Comprehensive in vivo study with animals having conditionally inactivated HIF-1α, HIF-2α, and FH genes revealed renal cyst formation and tumor development as being rather HIF-independent." (PMID 31963199, 2020). "In the invasive part, some proteins (RHOB or fumarate hydratase) also exhibited an elevated AngioScore but these proteins have been indeed extensively studied in the context of tumor angiogenesis." (PMID 32642662, 2019). "This concept was used to predict synthetic lethal partners of the known metabolic tumor suppressors fumarate hydratase (FH) and succinate dehydrogenase (SDH)." (PMID 31272436, 2019). "FH is known as a TCA cycle enzyme and tumour suppressor, and the deletion of FH leads to cellular fumarate accumulation and TCA cycle blockage." (PMID 30668541, 2019). "In tumor cells harboring mutant FH, an accumulation of fumarate results in succination of cysteine-modifying proteins such as kelch-like ECH-associated protein 1 (KEAP1) and mitochondrial aconitase (ACO2)." (PMID 28748451, 2018). "Mutations in fumarate hydratase (FH), succinate dehydrogenase﻿ ﻿(SDH)﻿﻿, and IDH1 and IDH2 are associated to specific human neoplasms that hence accumulate succinate, fumarate, and (R)-2-HG, respectively, all conveying broad oncogenic signals." (PMID 28184304, 2017). "Although tumor formation was a singular event, this was the first demonstration of malignancy development after FH-hTERT transplantation." (PMID 29383183, 2017).
tumor (continued). "Interestingly, the metabolic phenotype of FH-deficient cells can more effectively resist conditions that are otherwise unfavorable for mitochondrial function, including hypoxia, suggesting that these changes might be selected during tumor progression." (PMID 29069586, 2017). "The fact that metabolic enzymes such as succinate dehydrogenase (SDH) and fumarase (FH) function as tumor suppressors in human cells suggests that metabolic dysregulation can be an initiating event in cancer." (PMID 27565572, 2016). "FH is an enzyme in the tricarboxylic acid cycle that converts fumarate to malate and is thought to act as a tumour suppressor gene." (PMID 27144040, 2016). "Tumor specimens from patients with HLRCC demonstrate changes consistent with FH inactivation and pseudo-hypoxia." (PMID 27047799, 2016). "Dysfunctional FH in cells and tissues attributes to accumulating high levels of fumarate, which has been proposed to promote cancer development, indicating a tumor suppressor of FH." (PMID 27556703, 2016). "The accumulation of fumarate was also observed in cells depleted for FH or expressing a tumor-derived FH mutant." (PMID 26812134, 2016). "The remaining FH-negative/2SC-positive tumour (T41) harboured somatic homozygous deletion of the FH gene, revealing a somatic mechanism that can lead to FH functional loss." (PMID 27713405, 2016). "FH is emerging as an important mitochondrial tumour suppressor in both hereditary and sporadic forms of cancer." (PMID 25613188, 2015). "Mutations of the FH gene, including missense, frameshift, and complete or partial deletions, have been detected in 90% of HLRCC families, suggesting that the FH gene has the characteristics of a tumor suppressor gene." (PMID 24684806, 2014). "Such genetic mutations include the identification of two metabolic tumor suppressors in TCA cycle, fumarate hydratase (FH) and succinate dehydrogenase (SDH), and oncogene, isocitrate dehydrogenase (IDH), as well as other passenger loss-of-function mutations." (PMID 24568598, 2014). "The levels of succinate and fumarate in TCA cycle change and activate the related enzymes (SDH and FH); Fumarate is also implicated in control of the PHDs and HIF signal pathway, believed to be an important pathway in tumor development." (PMID 24958263, 2013). "Our results from HLRCC derived human tumor cell lines agree with the previous report on the effect of FH ablation in immortalized mouse kidney cells, where glutamine is oxidized through part of the Krebs cycle to produce NADH/FADH2 and high levels of fumarate." (PMID 23967283, 2013). "The recent identification of succinate dehydrogenase (SDH) and FH as mitochondrial tumor-suppressor genes has provided a direct link between dysfunctional mitochondria and cancer." (PMID 23643539, 2013). "Two possible candidate tumor suppressor genes located within the deleted segment are FH (fumarate hydratase) and EGLN1 (EGL nine homolog 1), implicated in other types of tumors." (PMID 23341988, 2013). "Tumor cells can tolerate such defects in the TCA cycle brought about by IDH1, FH or SDH mutation by redirecting the use of metabolites." (PMID 24350057, 2013). "SDH and fumarate hydratase are thought to act as tumor suppressor genes, with cancers exhibiting the “two-hits” typical of tumor suppressor gene inactivation." (PMID 23267435, 2012). "Quantitative real time RT-PCR demonstrated reduced FH mRNA levels in tumor tissue as compared with normal tissue." (PMID 21695080, 2011). "We then examined mRNA expression levels of FH in tumor tissue as compared to patient-matched normal renal tissue in specimens from the Cooperative Human Tissue Network (NCI)." (PMID 21695080, 2011). "To confirm our findings, we performed immunohistochemical staining for FH on patient matched tumor/normal pairs." (PMID 21695080, 2011). "In this regard, implication of FH in the DNA damage response, in this study, can in essence explain this tumor suppressor activity." (PMID 20231875, 2010).
tumor (continued). "The findings indicating that FH, a mitochondrial metabolic enzyme, is a tumor suppressor were fascinating." (PMID 20231875, 2010). "We suggest that the major function of FH as a tumor suppressor gene is due to its role in the cellular response to DNA DSBs." (PMID 20231875, 2010). "Succinate dehydrogenase (SDH) and fumarate hydratase (FH) are tricarboxylic acid (TCA) cycle enzymes that are also known to act as tumour suppressor genes." (PMID 19778456, 2009). "FH is a Krebs' cycle enzyme which is located in the cytosol or can be transported to the mitochondrion and has been shown to act as a tumor suppressor." (PMID 19308253, 2009). "Some studies found that FH+ tumours are more likely to be ER− and PgR−, have a higher proliferation rate and higher grading, but none of the others found any differences." (PMID 15162141, 2004). "Furthermore, we have shown that knocking down FH in a murine tumor model results in a reduction in the 13C‐malate/13C‐fumarate ratio, confirming that the method measures enzyme activity within tissue." (PMID 40331406, 2025). "Oncogenes and tumor suppressors regulate cycle flux by modulating fuel translocator and enzyme activities, with frequent mutations or dysregulation observed in cycle enzymes (aconitase, IDH, fumarate hydratase [FH], SDH and KGDHC) across cancer types." (PMID 41488637, 2025). "Although this study was based on the role of FH in tumor cell metabolism, it cannot be denied that FH may regulate some signal pathway." (PMID 41380966, 2025). "In control tumors (empty vector) where FH enzyme was present, a higher 13C‐malate/13C‐fumarate ratio was observed across all timepoints compared to knockdown tumors, indicating physiological conversion of fumarate to malate within the tumor." (PMID 40331406, 2025). "Alternatively, there may be some restoration of FH activity in tumor cells due to clonal expansion of populations with higher FH expression." (PMID 40331406, 2025). "Lysine succinylation may inhibit the activity of its protein substrates, such as phosphoenolpyruvate carboxylate kinase 2 (PCK2), aconitate hydrated hemitochondria (ACO2), and fumarate hydratase (FH), which regulate tumor phenotypes." (PMID 40865948, 2025). "While boosting immune function is essential for tumor elimination, it is still unclear whether dysregulation of fumarate hydratase (FH) expression or function in ccRCC affects tumor immune evasion or PD-L1 expression." (PMID 40461489, 2025). "Nevertheless, the connection between RBM15 and FH adds another layer to the understanding of anti-tumor immune responses, by which the m6A writer component suppresses the anti-tumor immunity through regulating key enzymes in carbon metabolism, leading to the release of immunosuppressive metabolites." (PMID 40370450, 2025). "Notably, increased FH expression, particularly within the nucleus, suggests enrichment in tumor cells." (PMID 40370471, 2025). "However, there are limited studies on the role of FH in tumour cells or on how FH activity is regulated." (PMID 40721560, 2025). "Fumarate hydratase (FH), a key node of mitochondrial metabolism, is also a tumour suppressor." (PMID 40721560, 2025). "Such tumor profiling could offer key insights—identifying particular somatic mutations (e.g., in VHL, FH, or BAP1) may prompt testing for the same mutation in germline DNA." (PMID 41562811, 2025). "FH-deficient low-grade morphology tumors are similar to high-grade morphology tumors in that they have a mixed tumor growth pattern, but current data on the former do not show a clear gender advantage, and their age of onset is relatively younger." (PMID 39659780, 2024).